ANGPTL4 (angiopoietin like 4)
Diseases named in the same sentence as ANGPTL4 in open-access papers (continued):
Sharing a sentence is not in itself a finding about the gene and the disease.
cancer (continued). "Before experimentally investigating the involvement of ANGPTL4 in this context, we ascertained in which type of cancer it may play a role." (PMID 41347893, 2026). "Therefore, our results substantiate the role of FFAs provided by adipocytes in inducing ANGPTL4 expression in cancer cells by acting as ligands for PPARα." (PMID 40616161, 2025). "This review examines the comprehensive biological functions of ANGPTL4 and its contributions to disease mechanisms with a specific emphasis on cancer, as well as its potential as a therapeutic target across different types of human cancers." (PMID 40723247, 2025). "Other possible causes of heterogeneity could be previous lines of therapy or purely due to the different role of ANGPTL4 in different cancer types." (PMID 40233044, 2025). "Furthermore, we identify cancers where ANGPTL4’s role in the TME, patient prognosis, and drug resistance is not yet explored, identifying potential new targets for treatment and biomarker selection." (PMID 40233044, 2025). "In cancer, ANGPTL4 has been shown to play varied roles depending on the type of cancer." (PMID 40723247, 2025). "Additionally, analysis using the Kaplan–Meier Plotter website showed that CFD was favorable for immunotherapy response, whereas ANGPTL4 negatively impacted the outcomes of cancer patients receiving immunotherapy." (PMID 40340806, 2025). "Furthermore, to elucidate the role of ANGPTL4 in cancer we conducted GSEA on the top 500 positively and negatively co-expressed genes." (PMID 40233044, 2025). "ANGPTL4 has been widely recognized as an oncogenic protein in both cancer and stromal cells." (PMID 40616161, 2025). "Finally, ongoing clinical trials investigating pharmacological ANGPTL4 inhibition for CVD present another opportunity to explore potential cancer preventive properties of these medications." (PMID 40511612, 2025). "Moreover, recent research has shown that IL-6 secreted by adipocytes drives STAT3 signaling to induce HIF1α in cancer cells, with HIF1α known to regulate ANGPTL4 expression." (PMID 40616161, 2025). "We employed drug-target Mendelian randomization (MR) to systematically evaluate the effect of 5 approved or emerging lipid-perturbing drug targets for CVD (APOC3, ANGPTL3, ANGPTL4, CETP, and PCSK9) on risk of 5 cancers (breast, colorectal, head and neck, ovarian, and prostate)." (PMID 40511612, 2025). "By integrating transcriptomic and proteomic data in multitrait colocalization, 13 pleiotropic loci influenced CAD and cancer risk via differential gene or protein expression of neighboring genes, including CALCRL, ANGPTL4, and LAMC1, targets of approved or investigational medications." (PMID 40874306, 2025). "Furthermore, studies have shown that ANGPTL1 exerts anti-angiogenic properties through its modulation of endothelial cells, while ANGPTL2 and ANGPTL4 play an integral part in the pro-angiogenic response to hypoxia exerted by different cancers." (PMID 40233044, 2025). "Furthermore, ANGPTL4 has been shown to both promote and inhibit metastasis based on different protein cleavage products and cancer types." (PMID 40233044, 2025). "For instance, recent studies have revealed that increased ANGPTL4 expression is closely associated with the invasiveness and drug resistance of KRASG12D pancreatic cancer, and researchers have explored the mechanisms of drug resistance in KRAS-mutant cancers." (PMID 38992710, 2024). "Furthermore, HIF-1 stimulates cancer cell extravasation by inhibiting vascular endothelial cell adhesion through the induction of angiopoietin-related protein 4 (ANGPTL4) activity." (PMID 39459028, 2024). "The role of ANGPTL4 in cancer progression depends on the cancer type." (PMID 39105498, 2024). "ANGPTL4 may be a key regulator in complex signaling pathways and enhance the malignancy of cancer cells through diverse functions." (PMID 38643448, 2024). "ANGPTL4 is a member of the angiopoietin family and over expressed in cancer tissue due to hypoxia." (PMID 38791417, 2024).
cancer (continued). "Decreased levels of ANGPTL4—coding for angiopoietin-like protein 4, which regulates lipid and glucose metabolism and the growth of new blood vessels—could lead to inhibition of angiogenesis in cancer cells." (PMID 37834191, 2023). "Specifically, ANGPTL4 has been found to play a role in the regulation of vascular permeability and angiogenesis, which has implications for the treatment of various vascular disorders, such as diabetic retinopathy and cancer." (PMID 38159259, 2023). "As such, ANGPTL4 represents an exciting therapeutic target in the fight against cancer." (PMID 38159259, 2023). "Moreover, angiopoietin-like 4 (ANGPTL4), a known proangiogenic factor in cancer, is induced by IL-1β from adipocytes in a manner dependent on NF-κB and MAPK." (PMID 36670988, 2023). "MMP17, PI3, TLL1, ANGPTL4, and TGFBI have all been previously associated with cancer." (PMID 37388244, 2023). "The application of ANGPTL4 as a cancer treatment target needs further research." (PMID 36553482, 2022). "However, the role of ANGPTL4 in cancers is controversial because studies reported contrary effects of ANGPTL4 in cancers, even in the same cancer." (PMID 35463073, 2022). "These enriched pathways were further observed to show ANGPTL4 is involved in lipid metabolism and might be, as previous studies proposed, an important cancer regulator." (PMID 36153524, 2022). "Because of its important role in lipid metabolism, ANGPTL4 was once considered a regulator of lipid metabolism, but, in recent years, studies have found that ANGPTL4 is closely related to the proliferation and metastasis of a variety of malignant tumours." (PMID 36467503, 2022). "Hence, ANGPTL4 is suggested to be a potential serum marker for some cancers, but its expression in tissues and serum of CCA patients has not yet been studied." (PMID 35392474, 2022). "In addition, ANGPTL4 was shown to be involved in temozolomide resistance in glioblastoma by promoting cancer stemness." (PMID 35461343, 2022). "Therefore, further investigation is required into ANGPTL4 regulatory circuits and the definition of specific molecular events that mediate its various biological functions in different cancer stages." (PMID 34685578, 2021). "We suspect that ANGPTL4 might also contribute because it is known to promote survival pathways in cancer cells." (PMID 34646996, 2021). "Secondly, enhanced glycolysis and ANGPTL4 expression may interfere with the efficacy of other anti-cancer drugs." (PMID 34646996, 2021). "Given the mounting evidence for the role of ANGPTL-3 and ANGPTL-4 in cancer, perhaps the hepatic microenvironment shaped by advanced fibrosis in F3 HCV patients could be the one that dictates the depth of ANGPTLs’ involvement in HCC development." (PMID 34360721, 2021). "However, the roles of ANGPTL4 in human cancers are controversial in different experimental models and proposed pathways." (PMID 34540685, 2021). "In the case of ANGPTL4, knockdown of its gene radically inhibited the extravasation of circulating cancer cells and the metastasis of cancer cells to the lungs, which may prove useful in therapy." (PMID 34445141, 2021). "ANGPTL4 expression is related to cancer cell aggressiveness and migration." (PMID 34708125, 2021). "Thus, further studies are needed to illuminate the potential mechanisms by which ANGPTL4 regulates cancer development." (PMID 32928141, 2020). "Second, despite discrepancies in these results, early studies have used various cancer cell samples, suggesting that the disparate influences of ANGPTL4 in cancer progression may be determined by cancer types." (PMID 32928141, 2020). "Similar autocrine action of ANGPTL4 was observed in cancer cells and endothelial cells." (PMID 32638512, 2020). "These conflicting phenomena might be given rise to the following possibilities: First, different ANGPTL4 fragments may have distinct biological roles in human cancers." (PMID 32928141, 2020).
cancer (continued). "However, many studies have reported that ANGPTL4 expression increases cancer cell aggressiveness and migration." (PMID 32928141, 2020). "The studies are controversial when considering ANGPTL-4 involvement in cancer." (PMID 31741709, 2019). "High expression of ANGPTL4 could also increase the anoikis resistance ability and promote cancer metastasis." (PMID 31198634, 2019). "Taken all together our results suggest that increased ANGPTL-4 levels may contribute for a proinflammatory environment on cancer cachexia patients." (PMID 31741709, 2019). "Cancer cells are also capable of secreting protein angiopoietin-like-4 (Angptl4), EREG, COX-2, MMP-1, and MMP-2 that may facilitate extravasation." (PMID 31133019, 2019). "Considering the effect of macrophage CM on the upregulation of factors to increase vascular permeability, both M1 and M2 CM-treated cancer cells showed increased expression of angiopoietin-like 4 (ANGPTL-4), and M2-CM-treated cells expressed higher levels of IL-18." (PMID 30218063, 2018). "The presence of different ANGPTL4-derived-peptide with tissue-dependent functions suggests that ANGPTL4 may have different roles in human cancers." (PMID 29389861, 2018). "The aberrant expression of ANGPTL4 was common to different aggressive cancers." (PMID 29389861, 2018). "The roles of ANGPTL4 in human cancers are most likely complex." (PMID 29389861, 2018). "However, is clear that ANGPTL4 posttranslational modification can affect its biological functions complicating further the role of ANGPTL4 in cancer." (PMID 29389861, 2018). "Recently, ANGPTL4 was suggested to be an important player in redox-mediated cancer progression." (PMID 29389861, 2018). "Overexpression of ANGPTL4 can further increase tumorigenesis, angiogenesis, metastasis but equally decrease vascular permeability, cells’ motility and invasiveness depending on the contexts of different cancers." (PMID 29389861, 2018). "Again, the importance of Aurora in the ANGPTL4-mediated up-regulation of TTP may be compromised when studied in cancer cell lines." (PMID 28287161, 2017). "In this complex scenario, we speculated on the potential role played by some “pleiotropic” molecules, such as PPARs isoforms and ANGPTL4, in connecting lipid and glucose metabolism with cancer." (PMID 28182091, 2017). "As SGC progresses, the cancer cells may acquire resistance to anoikis through ANGPTL4-dependent activation of FAK/Src/PI3K-Akt/ERK signalling, leading to the development of peritoneal metastasis." (PMID 28894280, 2017). "In addition, PPARβ/δ, via its regulation of ANGPTL4 gene expression, is suggested to be implicated in MDA-MB-231 cancer cell invasion into a three-dimensional matrix." (PMID 24203162, 2014). "Recently, emerging evidence has identified a novel role for ANGPTL4 in cancer development." (PMID 23925665, 2013). "Moreover, ANGPTL4 resulted in worse OS when combining all cancer types." (PMID 40233044, 2025). "The Massague laboratory first showed that ANGPTL4 could promote lung metastasis by disrupting the integrity of the cell–cell junctions of lung endothelial cells, facilitating the trans-endothelial migration of cancer cells." (PMID 40723247, 2025). "Therefore, although the relevance of ANGPTL4 in human cancer is undeniable and positions the protein as a possible therapeutic target, it demands caution as the functions appear to be tissue- and cancer-specific." (PMID 40723247, 2025). "Thus, ANGPTL4 may be a potential therapeutic target in cancer, but the context in which it may be beneficial needs further study." (PMID 40723247, 2025). "Also, such discrepancy might be due to the fact that the function of ANGPTL4 in cancer progression may be determined by CCA subtypes." (PMID 35392474, 2022). "However, other studies have also confirmed that ANGPTL4 seems to promote cancer development." (PMID 35692877, 2022).
cancer (continued). "Moreover, as a secretory glycoprotein, ANGPTL4 protein is widely regarded as a decisive regulator of angiogenesis and an inflammatory carcinogenic mediator that participates in the occurrence of human cancer in the manner of autocrine and paracrine activity." (PMID 36050447, 2022). "Thus, ANGPTL4 may act as a powerful autocrine and paracrine signaling effector of PPARs that can shape a supportive environment for cancer progression." (PMID 33946986, 2021). "In addition, these contradictory findings suggest a multifaceted role for ANGPTL4 in human cancers." (PMID 34685578, 2021). "However, many studies of other types of cancer suggest that ANGPTL4 functions as an oncogene." (PMID 34685578, 2021). "However, some studies have indicated that ANGPTL4 has an opposite role in cancer progression." (PMID 31963541, 2020). "However, the role of ANGPTL4 expression in different kinds of malignancies appears to be different, and the precise function of this protein in cancer biology remains unclear." (PMID 32928141, 2020). "Therefore, the regulation of ROS production in the presence of increased FFA levels may be caused by ANGPTL4 secretion, which leads to NOX4 expression and cancer metastasis." (PMID 32641980, 2020). "However, the role of ANGPTL4 in cancer remains controversial." (PMID 31717924, 2019). "Notably, palmitate and linoleate also induced ANGPTL4 gene expression in these cancer cells." (PMID 29163362, 2017). "However, it has been reported that ANGPTL4 promotes cancer growth and progression." (PMID 25370833, 2015). "Eight proteins (C-reactive protein, AGRN, XPOT, LDHA, C1QC, ORM1, ANGPTL4, and prostaglandin D2 synthase [PTGDS]) exhibited a continuously upward or downward trend in three or more cancer types." (PMID 39884577, 2025). "VEGF proteins were particularly abundant in all cancer and endothelial cell secretomes, whereas ANG and ANGPT2/ANGPTL4 in SK-OV-3, suggesting a potentially significant role in the formation of the HBEC-5i/SK-OV-3 networked constructs." (PMID 41279931, 2025). "These included multitrait colocalization at 6 loci with a consistent direction of effect between CAD and cancer (ABO, PGAP3, ANGPTL4, SREBF1, HAUS6, and SYNJ2BP) and 7 with an opposing direction (CDKN1A, RGS19, CALCRL, SF3A3, LAMC1, MYO9B, and MIA3)." (PMID 40874306, 2025). "Angiopoietin like 4 (ANGPTL4), an adipokine involved in lipid and glucose metabolism, plays a critical role in cancer development." (PMID 38643448, 2024). "Angiopoietin-like 4 (ANGPTL4), which is induced by hypoxia in a HIF-1-dependent manner, disrupts vascular EC-EC junctions and facilitates the extravasation of cancer cells." (PMID 39434182, 2024). "The protein expression levels of PLK1, SLC2A1, ANGPTL4, and CDKN3 in LUAD tissues were all significantly higher than those in para-cancer tissues." (PMID 38345559, 2024). "Activation of HIF‐1α triggers the transcription of genes involved in cancer and immunity, including cytokines IL8, IL6, ANGPTL4, VEGF and PDGF, which are commonly observed in SASP." (PMID 36660875, 2023). "We further found that ANGPTL1, ANGPTL3, ANGPTL4, and ANGPTL8 were significantly highly expressed in HCC cell lines than other types of cancer cell lines (p < 0.05)." (PMID 35692877, 2022). "Considering the similarities in excessive cell proliferation between human cancer cells and PASMCs of PAH, it is very likely that ANGPTL4 plays some roles in PAH." (PMID 35893764, 2022). "The metastatic potential of cancer can be enhanced by HIF-1α target genes, such as angiopoietin-like 4 (ANGPTL4), lysyl oxidase (LOX), and lysyl oxidase-like 4 (LOXL4)." (PMID 34575983, 2021). "Astrocyte–cancer cell communication is also mediated by TGF-β2 and ANGPTL4, the latter of which is an effector of PPARs." (PMID 33946986, 2021). "ANGPTL4, BHLHE40, and VEGF are considered as critical genes in cancer studies, which play pivotal roles in biological processes and are somehow regulated by HIF1α." (PMID 33602983, 2021).
cancer (continued). "In some studies, ANGPTL4 has been shown to be regulated by PI3K/AKT pathway in endothelial, cancer cells, and stem cells." (PMID 32638512, 2020). "After 24-h treatment, the expression of nickel-induced ANGPTL4 and HIF-1α was significantly suppressed by metformin in both lung epithelial cells and cancer cells." (PMID 31963541, 2020). "Based on our findings, Sp4-regulated ANGPTL4 production promotes the malignancy of GBM, including the acquirement of drug resistance, by inducing cancer stem cell enrichment." (PMID 31717924, 2019). "Molecular method was based on the analysis of selected genes expression related to hypoxia (HIF1A, ANGPTL4, TGFB1, VEGFA, ERBB3, CA9) or specific for inflammation in hypoxic sites (CCL2, CCL5) at various time points after CT26 cancer cells inoculation." (PMID 30412628, 2018). "This overlap includes numerous PPARG target genes, including ANGPTL4 and AQP7, which were two of the six most highly induced genes in the human PPFP carcinomas." (PMID 26595524, 2015). "Specific neutralizing antibodies against ANGPTL4 that antagonize the interaction between ANGPTL4 and integrins result in a dose-dependent reduction in the O2− : H2O2 ratio and increased apoptotic cancer cells." (PMID 22481923, 2012). "Notably, PPARD was reported to bind PPREs in the promoters of ANGPTL4 and PDK4 in cancer cells, leading to their upregulation." (PMID 40652248, 2025). "Moreover, we examined the protein expression levels of the four ARGs (PLK1, SLC2A1, ANGPTL4, CDKN3) in cancer tissues and para-cancer tissues from clinical LUAD patients." (PMID 38345559, 2024). "VEGFA, PDGFRB, ANGPTL4 and ENG have been shown to play major roles in angiogenesis and vascular homeostasis, not only in physiological regeneration but also in most pathological angiogenic processes such as cancer." (PMID 38882056, 2024). "Considering that various factors, including ANGPTL4, contribute to the extravasation of cancer cells, we cannot rule out the possibility that factors beyond E-cadherin are implicated in the ELK3-ID4 axis-mediated extravasation of TNBC." (PMID 38188675, 2023). "The picture, however, is not perfectly clear since ANGPTL4 expression seems to have different impacts in cancers of different primary sites." (PMID 37291514, 2023). "Angiopoietin-like-4 (ANGPTL4), a secreted glycoprotein that is mainly known as a regulator in lipid metabolism, now, is also indicated to be involved in the regulation of cancer progression and metastasis." (PMID 35461343, 2022). "More recent observations support a model in which supernumerary centrosomes in cancer cells can promote the overproduction and secretion of cytokines and pro-invasive factors, such as IL-8, ANGPTL4 (Angiopoietin Like 4), and GDF-15 (Growth Differentiation Factor 15)." (PMID 33922633, 2021). "For instance, ANGPTL4 could be induced by hypoxia through upregulation of PGE2 receptor in CRC, thus promoted cancer cell proliferation." (PMID 32410376, 2020). "In addition, upon adhesion of cancer cells to endothelial cells they secrete cytokines and growth factors, such as VEGF, angiopoietin 2 (Angpt2), and angiopoietin-like 4 (Angptl4), leading to hyperpermeability of the endothelial wall." (PMID 33747899, 2020). "To determine whether ANGPTL4 overexpression correlates with the prognosis of TNBC, we analyzed the level of flANGPTL4 in cancer cells by IHC." (PMID 32928141, 2020). "Although ANGPTL4 was highly expressed in adipocytes and epithelial cells, we only focused on the role of flANGPTL4 from cancer cells, not stromal cells." (PMID 32928141, 2020). "In cancer, the cognitive receptor for GDF-15 is unknown; however, the C-terminal fragment of ANGPTL4, used in this study, can bind and activate β1 and β5 integrins, which could aid invasion." (PMID 30458137, 2018). "To date, the role of ANGPTL4 in cancer progression is not well defined, and there is still some controversy in the literature indicating the need of more studies addressing this interesting topic." (PMID 28182091, 2017).